MERTK (MER proto-oncogene, tyrosine kinase)
Description:
Receptor tyrosine kinase that transduces signals from the extracellular matrix into the cytoplasm by binding to several ligands including LGALS3, TUB, TULP1 or GAS6. Regulates many physiological processes including cell survival, migration, differentiation, and phagocytosis of apoptotic cells (efferocytosis). Ligand binding at the cell surface induces autophosphorylation of MERTK on its intracellular domain that provides docking sites for downstream signaling molecules. Following activation by ligand, interacts with GRB2 or PLCG2 and induces phosphorylation of MAPK1, MAPK2, FAK/PTK2 or RAC1. MERTK signaling plays a role in various processes such as macrophage clearance of apoptotic cells, platelet aggregation, cytoskeleton reorganization and engulfment. Functions in the retinal pigment epithelium (RPE) as a regulator of rod outer segments fragments phagocytosis. Also plays an important role in inhibition of Toll-like receptors (TLRs)-mediated innate immune response by activating STAT1, which selectively induces production of suppressors of cytokine signaling SOCS1 and SOCS3.
Synonyms: MER; RP38; c-Eyk; Tyro12; c-mer
Tractability: Small molecule: a drug acting on it is in phase 2 or 3 trials; a structure with a bound ligand is known; a high-quality ligand is known; it has a high-quality binding pocket; it belongs to a druggable protein family. Antibody: UniProt places it where antibodies can reach, with high confidence; its Gene Ontology location is reachable by antibodies, with high confidence; UniProt predicts a signal peptide or a membrane-spanning region; the Human Protein Atlas places it where antibodies can reach. PROTAC: it is named in the literature on targeted protein degradation; ubiquitination databases record sites on it; its protein half-life has been measured; a small molecule that binds it is known.
Target class: Tyrosine protein kinase Axl family; Protein Kinase; Kinase; TK protein kinase group; Enzyme
Chemical probes: UNC2025 (high quality), UNC2881
Gene: Protein-coding gene on chromosome 2 (111,898,607 to 112,029,561, forward strand). Ensembl gene ENSG00000153208.
Subcellular location: Cell membrane
Subcellular location (Human Protein Atlas): Plasma membrane; Acrosome; Cytosol; Mid piece; Midbody; Principal piece
Pathways (Reactome):
Disease: Dengue Virus Attachment and Entry
Hemostasis: Cell surface interactions at the vascular wall
Gene Ontology:
Molecular function: protein binding; transmembrane receptor protein tyrosine kinase activity; ATP binding; protein kinase activity; protein tyrosine kinase activity
Biological process: negative regulation of leukocyte apoptotic process; phagocytosis; positive regulation of phagocytosis; cell migration; cell surface receptor protein tyrosine kinase signaling pathway; cell surface receptor signaling pathway; cell-cell signaling; nervous system development; protein phosphorylation
Cellular component: cytoplasm; extracellular region; plasma membrane; endosome membrane; receptor complex; photoreceptor outer segment
Genetic constraint (gnomAD): Loss-of-function variants: 60 observed, 94.48 expected, observed/expected ratio (o/e) 0.64, 90% interval 0.51 to 0.79. The upper end of that interval is the gene's LOEUF score, 0.79, which puts it in group 3 of 6, group 1 being the genes least tolerant of losing a copy. Missense variants: 1,087 observed, 1,259 expected, observed/expected ratio (o/e) 0.86, 90% interval 0.82 to 0.91. Synonymous variants: 410 observed, 473.99 expected, observed/expected ratio (o/e) 0.86, 90% interval 0.8 to 0.94.
Homologues: Orthologues: macaque MERTK (96% identical), chimpanzee MERTK (93% identical), dog MERTK (85% identical), pig MERTK (84% identical), rabbit MERTK (81% identical), mouse Mertk (81% identical), rat Mertk (80% identical), guinea pig MERTK (72% identical), tropical clawed frog mertk (53% identical), zebrafish mertka (44% identical). Paralogues in human: AXL (37% identical), TYRO3 (34% identical), ROS1 (23% identical), MET (23% identical), IGF1R (20% identical), MST1R (20% identical), INSR (19% identical), KDR (18% identical), INSRR (18% identical), FLT4 (18% identical), FLT1 (18% identical), TIE1 (18% identical), and 41 more.
Diseases named in the same sentence as MERTK in open-access papers:
MERTK is named in the same sentence as 274 diseases in open-access papers, as found by Europe PMC text mining. Sharing a sentence is not in itself a finding about the gene and the disease. The quoted sentences say what the papers report.
melanoma (44 papers, 2014 to 2025). A malignant, usually aggressive tumor composed of atypical, neoplastic melanocytes. "Axl and MerTK are closely related RTKs that have both been associated with drug resistance and immunological resistance in melanoma Antibody-mediated inhibition of Axl appeared to restore patient susceptibility to BRAF inhibitors." (PMID 38067178, 2023). "Shedding of Axl and MerTK associates with dampening of TAM signaling in melanoma or breast carcinoma as well as in liver fibrosis." (PMID 34771611, 2021). "The overexpression of MERTK was observed in melanoma cells with the BRAF V600E mutation, which are resistant to BRAF and MEK inhibitors." (PMID 33562150, 2021). "Simultaneous inhibition of mutant BRAF and autophagy efficiently induced caspase 3 cleavage in 7 melanoma cell lines, which mimicked the phenotype of cells with loss of MerTK when exposed to BRAFi stress as previously observed." (PMID 29050198, 2017). "Our data highlight a novel mechanism of mTORC1/autophagy/MerTK-mediated resistance to BRAFi in melanoma harbouring BRAFV600E mutation." (PMID 29050198, 2017). "MERTK has been implicated in the tumorgenesis of several cancers such as melanoma, astrocytoma as well as gastric and non-small cell lung cancer." (PMID 27081701, 2016). "Furthermore, when melanoma cell lines were associated to usual human melanocytes, almost half of them showed MERTK overexpression." (PMID 41166341, 2025). "Consistently, loss of MerTK sensitized melanoma cells to apoptosis upon BRAF inhibition, as determined by increased accumulation of cleaved Caspase 3, suggesting that MerTK is a critical mediator regulating cellular responses in order to antagonize apoptotic stress." (PMID 29050198, 2017). "A number of receptor tyrosine kinases (RTKs) are implicated in the pathogenesis of cancer, and among them, aberrant activation of the TAM (Tyro-3, Axl, and MerTK) family of RTKs is known to be associated with pathogenesis of several malignancies, including melanoma, leukemia, and glioma." (PMID 29228560, 2017). "Interestingly, the growth of melanoma and mammary tumors was significantly inhibited in MERTK−/− host mice, owing to elevated pro-inflammatory (M1-like) cytokine levels in MERTK-deficient CD11b+ cells, compared to mice fully expressing MERTK in the host." (PMID 31775787, 2019). "Previous studies have reported that MerTK promotes melanoma cell migration and glioma multiforme cell migration, invasion, and survival." (PMID 41226428, 2025). "MRX-2843 and related MERTK TKIs mediate direct tumor cell killing in preclinical models and promote sensitivity to chemotherapy in vitro and in murine models of leukemia, melanoma, lung cancer, and many other malignancies." (PMID 39199601, 2024). "Accordingly, MerTK is overexpressed as an abnormal finding in many human cancers including melanoma, leukemia, and prostate, lung, breast and liver cancer." (PMID 38341954, 2024). "In fact, in the analysis of melanoma patients, the level of MERTK+ MDSCs was far higher than those expressing AXL or TYRO3." (PMID 39062902, 2024). "MERTK is a protein found in leukemia, melanoma, lung cancer, and other cancer types where it promotes cancer cell survival and resistance to therapies." (PMID 39199601, 2024). "Correspondingly, MerTK inhibition promoted the apoptosis of melanoma cells, along with suppression of tumor proliferation and growth." (PMID 38067178, 2023). "Some studies have found that the expressions of Tyro3, Ax1, MERTK and their ligands of MDSCs in tumor-bearing (melanoma) mice are significantly up-regulated, which can inhibit the ability of T cells to migrate to tumor draining lymph nodes." (PMID 37221594, 2023). "As a member of the TAM receptor family (TYRO3, AXL, MERTK), MERTK is overexpressed in many solid cancers (such as breast cancer, colorectal cancer, and melanoma) as well as in hematological malignancies such as acute myeloid leukemia (AML)." (PMID 34835225, 2021).
melanoma (continued). "MDSCs from melanoma bearing mice express high levels of Tyro3, Axl, and MerTK, and MDSCs derived from Tyro-/-, Axl-/-, and MerTK-/-express higher levels of immunosuppressive molecules such as Arg-1, TGF-β, and IDO." (PMID 34771611, 2021). "Recent studies demonstrated that MerTK is over-expressed in lymphoma and melanoma and the inhibition of MerTK leads to suppression of tumour growth via AKT and Erk signaling." (PMID 33139930, 2021). "The MERTK expression is correlated with the melanoma disease progression and the suppression of MERTK is found to inhibit melanoma cell proliferation and migration in vitro." (PMID 34830178, 2021). "Further, intervention with Axl or MerTK activation favors sensitivity to PD-1 inhibition in breast cancer and melanoma." (PMID 34771611, 2021). "MerTK and Axl are also aberrantly expressed in a range of both hematological and solid tumor malignancies, including breast, lung, melanoma and acute myeloid leukemia, where they have a role in oncogenic signaling." (PMID 33801886, 2021). "MERTK is involved in multiple malignancies, including leukemia, glioma, melanoma, and rhabdomyosarcoma, while it has been described as novel therapeutic target in several of these malignancies." (PMID 34885181, 2021). "INCB081776 effectively blocked MERTK phosphorylation induced by MAB8912 in G361 melanoma cells with an IC50 value of 6.5 ± 3.1 nM (N = 4)." (PMID 33425754, 2020). "In comparison, the expression profiles of the other TAM receptors Axl and MerTK were more discrete, with strong expression of Axl observed in breast cancer and glioma cells, whilst MerTK was most highly expressed in melanoma and kidney cancer cells." (PMID 31766614, 2019). "Mer tyrosine kinase (MerTK) has been reported to be aberrantly expressed in leukemia, melanoma, and gastric cancer, and plays a pivotal role in the process of oncogenesis." (PMID 29554921, 2018). "These include two different mouse monoclonal antibodies raised against the extracellular domain of human TYRO3 that block GAS6-induced TYRO3 signaling in melanoma cells and have low cross-reactivity with MERTK and AXL." (PMID 30501104, 2018). "In melanoma and glioblastoma cells, MerTK inhibition mediated abrogation of migration and invasion by altering signaling through total and phosphorylated FAK, RhoA, and total and phosphorylated myosin light chain 2 (MLC2)." (PMID 29554921, 2018). "As in other RTK family proteins, aberrant expression of MerTK in various malignant tumors, such as melanoma, gastric cancer, leukemia, and lung cancer, plays a pivotal role in the process of oncogenesis." (PMID 29554921, 2018). "To explore the molecular details how MERTK was regulated, we analyzed the transcription factors that were co-upregulated in two melanoma cell lines (A375p and A2058) treated with PLX." (PMID 29050198, 2017). "We conducted transcriptome gene profiling in BRAFi-treated melanoma cells and identified that Mer tyrosine kinase (MerTK) is specifically upregulated." (PMID 29050198, 2017). "Knockdown of MERTK with three different shRNAs led to a similar phenotype in A2058 melanoma cells (constitutively expressing MerTK) grown on matrigel, although cell proliferation was not affected." (PMID 29050198, 2017). "In agreement with the in vitro studies, in the four paired human melanomas where MerTK is overexpressed post-vemurafenib therapy, nuclear accumulation of Zeb2 is broadly present in resistant tumors." (PMID 29050198, 2017). "Compared with untreated human melanomas, increased expression of MerTK was detected in the tumours from vemurafenib-treated patients." (PMID 29050198, 2017). "Mechanistically, BRAFi-induced activation of Zeb2 stimulates MerTK in BRAFV600 melanoma through mTORC1-triggered activation of autophagy." (PMID 29050198, 2017). "Studies in melanoma, gastric and lung cancer as well as astrocytoma showed a positive relation between MERTK and pAKT expression and increased apoptosis upon MERTK knockdown or inhibition." (PMID 27081701, 2016).
melanoma (continued). "Although higher MERTK protein expression was for example found in astrocytoma, glioma, melanoma as well as non-small cell lung, breast, and gastric cancer, only the last study investigated MERTK expression in context with clinico-pathological data." (PMID 27081701, 2016). "MERTK-expressing melanoma cells are more proliferative than AXL-expressing cells, though the latter are more invasive." (PMID 24743024, 2014). "Notably, the expression of MERTK was maximum in metastatic melanomas, subsequent to primary melanomas, and lowest in nevi." (PMID 41166341, 2025). "While inhibiting MerTK in other cancers (e.g., melanoma, pancreatic, colon cancers, and hepatocellular carcinoma) suppresses pro-tumor immune cells and cytokines, in TNBC MerTK overexpression uniquely enhances anti-tumor immune infiltration in murine 4T1 tumors." (PMID 40391157, 2025). "Our previous study and several other reports have shown that MerTK is overexpressed in different types of cancer including non-small cell lung cancer, breast cancer, blood cancer, head and neck cancer, melanoma, leukemia, and glioblastoma." (PMID 38791148, 2024). "MerTK expression is upregulated in BRAFi-resistant melanoma cells and TAMs." (PMID 38067178, 2023). "Interestingly, when drugs inhibit the expression of Tyro3, Ax1 and MERTK in vivo, melanoma growth slows down, CD8+T cell infiltration increases, and anti-PD-1 checkpoint inhibitor immunotherapy is enhanced." (PMID 37221594, 2023). "Here, we show that BAP1 loss leads to increased expression of PROS1 in uveal melanocytes and melanoma cells, which in turn leads to phosphorylation and activation of the receptor tyrosine kinase MERTK on adjacent macrophages, driving them into a suppressive M2-polarized state." (PMID 35954340, 2022). "The TAM family are implicated in regulating MDSC function, since increased MDSC expression of TYRO3, AXL and MERTK and their ligands was detected in a syngeneic mouse model of melanoma, and circulating MERTK+ and TYRO3+ MDSCs were more abundant in patients with metastatic melanoma." (PMID 36175961, 2022). "Furthermore, MERTK inhibition decreased colony formation, invasion, and xenograft growth in a human melanoma murine xenograft model." (PMID 33562150, 2021). "Interestingly, MERTK has been described as a therapeutic target in several cancers, including melanoma, leukemia, glioblastoma, and gastric cancer." (PMID 34885181, 2021). "To answer this question of how MerTK inhibition may affect MerTK+ T cells in an antitumor cell response, we studied MerTK signaling in melanoma TILs by examining the impact of Pros1." (PMID 33801886, 2021). "MerTK and Axl are expressed in a wide range of cancer types, including non-small cell lung cancer, breast cancer, colorectal cancer, ovarian cancer and melanoma, with 50–70% of patient samples being positive." (PMID 33801886, 2021). "MERTK is amplified in a small percentage of esophageal carcinomas and is overexpressed in the absence of gene amplification in many cancers, including multiple myeloma, gastric, prostate, breast, melanoma, and rhabdomyosarcoma." (PMID 33425754, 2020). "Moreover, they express higher levels of TAM-related markers (CD206, MerTK and CD163), compared to blood circulating CD14+ DCs, we previously linked to lower immunological response to DC-based vaccines in melanoma patients." (PMID 32488012, 2020). "Similarly, the potency of INCB081776 in blocking MERTK autophosphorylation was evaluated in G361 cells, a melanoma cell line expressing high level of MERTK." (PMID 33425754, 2020). "In addition, MERTK-activation by exogenous PROS1 supplementation increased cytotoxicity of tumor infiltrating lymphocytes against autologous melanoma cells, despite high level of MERTK expression by the autologous tumor cell line." (PMID 31664482, 2020). "Therefore, we propose that simultaneous targeting of BRAFV600E and autophagy/MerTK signaling axes is a rational strategy for overcoming resistance to BRAF inhibitors in melanoma." (PMID 29050198, 2017).